CCR2 (C-C motif chemokine receptor 2)
Diseases named in the same sentence as CCR2 in open-access papers (continued):
Sharing a sentence is not in itself a finding about the gene and the disease.
tumor (continued). "For example, agents targeting the CCL2/CCR2 axis have shown promise in reducing the recruitment of monocyte-derived TAMs, while inhibitors of colony-stimulating factor 1 receptor (CSF1R) blunt TAM support for tumor growth." (PMID 40330466, 2025). "Furthermore, in mice, CCR2, along with its ligands CCL2 and CCL7, is essential for the migration of MDSCs from the bloodstream to the tumor." (PMID 41368628, 2025). "Accordingly, tumor cell-derived supernatant induced monocyte recruitment of wt and Ccr1-/- monocytes, but not of Ccr2-/- monocytes, which is in agreement with previous studies." (PMID 39566333, 2025). "Additionally, azvudine regulated the interactions from other tumor immune cells to CD4+ T and CD8+ T cells through ligand‒receptor pairs such as COL1A2‒(ITGA1 + ITGB1), CCL4‒CCR5, CCL6‒CCR2, and CXCL16‒CXCR6." (PMID 39819859, 2025). "High levels of CCR2, CCR5, and CXCR4 at 1 week further supported active DC trafficking toward lymphoid tissues and tumor sites, while increased IL-10 may reflect early regulatory feedback within an immunostimulatory context." (PMID 41278869, 2025). "Besides, the multiplex immunofluorescence (mIF) staining analysis further confirmed the high infiltration of CCR2+ TAMs (CCR2+F4/80+) and a reduction in CD8+ T cells in the residual post-iIRE tumor." (PMID 40700478, 2025). "Inflammatory monocytes, which highly express CCR2 and respond to CCL2 produced by tumor and stromal cells, are recruited to metastatic sites such as the lungs and liver before tumor cells and differentiate into MAMs, secreting VEGF and promoting tumor cell metastasis." (PMID 41341593, 2025). "Therefore, we rationally designed proteolipid nanovesicles coloaded with the CCR2 antagonist PF-4136309 and GEM for highly efficient tumor combination chemoimmunotherapy." (PMID 40700478, 2025). "Notably, C-C chemokine receptor type 2 (CCR2) antagonist, RS504393, effectively reversed these F. nucleatum-mediated pro-tumor effects." (PMID 41276817, 2025). "Mechanistically, tumor-derived exosomes may carry chemokines (i.e., CCL2) that, by interacting with cognate receptors (i.e., CCR2), promote the uptake of exosomes by myeloid cells at metastatic sites." (PMID 41282257, 2025). "Our results show that although Roscovitine alone induces a favorable TME by lowering PD-L1 expression, increasing CD8+ and NK cell infiltration, and reducing CCR2+ MDSCs, these changes did not decrease tumor growth or increase survival." (PMID 41561738, 2025). "Therefore, using PF to inhibit CCR2+ TAM–induced immunosuppression is expected to enhance the therapeutic index of GEM and holds promise for mitigating post-iIRE tumor recurrence." (PMID 40700478, 2025). "CCR2 is the cognate receptor to the CC-chemokine, monocyte chemotactic protein 1 (MCP-1), also known as CCL2, which is widely secreted by hepatocytes, Kupffer cells, hepatic stellate cells, liver sinusoidal endothelial cells and HCC tumour cells." (PMID 39684877, 2024). "While the CCR2/CCL2 axis may recruit myeloid cells that are hijacked by the tumour to become immunosuppressive, these cells can promote an anti‐tumour response when activated to a pro‐inflammatory state." (PMID 38426634, 2024). "Within the tumor colonies, CCR2+ nonclassical monocytes secreted CCL6 to recruit NK cells that mediated tumor regression, independent of T and B lymphocytes." (PMID 39545417, 2024). "Furthermore, CCR2 antagonists (RS504393 and RS102896) have been developed to suppress tumor metastasis." (PMID 38338674, 2024). "In the xenograft mouse model, the supernatant from the co‐incubation of macrophages and oestrogen‐treated SKOV3 exosomes could promote tumour growth, as well as CCL13 treatment, which were suppressed by CCR2 knockdown." (PMID 38680032, 2024). "Despite being well-tolerated, carlumab did not effectively block the CCL2/CCR2 axis or demonstrate anti-tumor activity as a single agent in mCRPC." (PMID 39518123, 2024).
tumor (continued). "Additionally, a differential expression of the cytokine genes CCL2, CCL20, TGFB1, and TGFB2; the transcription factor gene IRF4; and the receptor genes CCR2, IL10RB, TGFBR1, and TGFBR2 was identified in tumor tissue and vestibular nerve tissue." (PMID 39272860, 2024). "Targeting the CCL2/CCR2 has shown some promise in preclinical murine models of HCC, with the CCR2 antagonists, RDC018 and 747, exhibiting good efficacy in an orthotopic liver tumour model, significantly restricting tumour growth and metastasis." (PMID 39684877, 2024). "Furthermore, the combination of CCR2 (the receptor for CCL2) inhibition and anti-PD-1 therapy has been shown to enhance tumor responses over anti-PD-1 monotherapy through enhanced recruitment and activation of CD8+ T-cells." (PMID 38575562, 2024). "Additionally, combining the CCR2 antagonist, RS504393, with anti-PD-1 therapy resulted in a superior tumor response compared to anti-PD-1 monotherapy in various murine tumor models." (PMID 38957393, 2024). "Tumor-resident mesenchymal stem cells, known for their significant secretion of a variety of chemokines, including CCL-2, CCL-7 and CCL-12, enhance the recruitment of CCR2-expressing monocytes to tumor sites, thereby increasing the macrophage population." (PMID 38575562, 2024). "In the circulation, some CCR2-expressing classical monocytes lose CCR2 and differentiate into intravascular nonclassical monocytes that have anticancer properties but are unable to access extravascular tumor sites." (PMID 39545417, 2024). "Moreover, the inclusion of chemokine receptors like CCR2 can enhance the migration and infiltration of CAR-NK cells into tumor tissues, thereby improving their tumor-killing potential.." (PMID 38263004, 2024). "Dual treatment with CCR2 and CXCR2 inhibitors can significantly increase the suppression of tumor-infiltrating myeloid cells in PDAC compared with either strategy alone and enhance the chemotherapeutic efficacy of FOLFIRINOX (5-Fluorouracil, irinotecan, and oxaliplatin)." (PMID 38672552, 2024). "CCL2, CCR2, CD163, and CD4 were all widely expressed in both CNB and resected tumor samples." (PMID 37208442, 2023). "This indicated complete tumor rejection in the majority of the UBC-GFP cohort, which was contrary to our expectations given that 100% (9 of 9) of tumors took in another tolerized strain: Cx3cr1-GFP;CCR2-RFP mice, with final tumor burden similar to that of NOD-SCID mice (p = 0.78)." (PMID 36637515, 2023). "Therefore, besides boosting tumor specific cytotoxic T cell responses, future immunotherapeutic vaccination approaches must focus on the immunosuppressive TME, including CCR2+ monocytes." (PMID 37849753, 2023). "To further test the utility of assessment of early TME responses to Treg cell depletion for identifying combinatory therapeutic modalities, we subjected KP tumor transplanted mice to a similar short-term treatment with CCR8 antibody and a selective CCR2 antagonist RS-504393 (CCR2i)." (PMID 37127830, 2023). "CCR2, the CCL2 receptor, represents another way of targeting CCL2 release, that in combination with anti-PD-1 therapy resulted in sensitization and increased tumor response compared to monotherapy." (PMID 38313431, 2023). "One study showed that CCR2 blockade by a CCR2 antagonist in vivo decreased the number of M2 macrophages, increased the number of IFNγ + CD8 + T cells, and inhibited tumor growth, indicating that M2 macrophage-mediated indirect effects significantly affect tumor growth." (PMID 37865750, 2023). "Considering that radiotherapy is widely used in tumor treatment, whether reducing MDSCs migration by inhibiting CXCR2 and CCR2 signaling can promote the therapeutic effect of radiotherapy will be the focus of our subsequent study." (PMID 37268941, 2023).
tumor (continued). "Infiltration of Ly6Chigh monocytes was reduced by 3- to 7-fold in all models; however, a significant reduction (more than 2-fold change) in tumor-infiltrating macrophages (TIMs) (CD11b+Ly6G−Ly6C−F4/80+) was observed only in MES tumors, indicating that CCR2 dependency was MES specific." (PMID 37208442, 2023). "These genes include markers of alternative macrophage polarization (Arg1, Cd163), monocyte chemoattractant Ccl6, and ligands for CCR2 (Ccl2, Ccl7, Ccl12) and CCR5/1 (Ccl3, CCl4, Ccl9) suggesting that F4/80+ cells in these tumours represent an increase in TAM2‐like myeloid cells." (PMID 35924447, 2023). "Collagen-endocytosing TAMs derived from CCR2+ inflammatory monocytes recruited to and altered the TME through endocytic collagen turnover, which further centrally engaged in collagen degradation and promote invasive tumor growth." (PMID 37040518, 2023). "Consistently, T-MPs neither promoted moDCs increase in dLN from CCR2−/− mice, nor triggered anti-tumor immune response." (PMID 37089435, 2023). "Expression of CXCR3, CXCR6, CCR2, and CCR5 differed between trNK cells, ILCs, CD8+ TRM cells, and CD4+ TRM cells, as well as between locations within the tumor and tumor-distal lung tissue." (PMID 37448786, 2023). "Despite the role of CCL2 in recruiting both cytotoxic T cells (CTL) and monocytes to tumor sites, studies have shown that enhancement of the CCL2/CCR2 axis or inhibition of CCL2 nitration in antitumor therapy significantly promotes T-cell infiltration and exerts antitumor effects." (PMID 36674931, 2023). "The expression by tumor-infiltrating NK cells of certain chemokine receptors including CCR2, CCR5, CCR7 and CX3CR1, and the abundance of their respective ligands in the TME has been correlated to enhanced NK cell tumor infiltration and improved cytotoxic response." (PMID 37298470, 2023). "CCL2 did not directly affect tumor cell proliferation because tumor cells isolated from neu+, Ccl2-/- neu+, and Ccr2-/- neu+ mice grew at similar rates in vitro." (PMID 37208442, 2023). "Next, we characterized the anti-inflammatory phenotype of CCR2+ Tumor-infiltrating monocytes, absent in DIVA2-treated mice during immune control, but detectable during immune evasion." (PMID 37849753, 2023). "Thus, HSPCs move to spleen via GM-CSF and CCR2/CCL2 axis and where they are primed to become immunosuppressive MICs to support tumor growth and metastasis via supporting immunosuppressive TIME." (PMID 37380989, 2023). "A recent study showed that ID8 injection in Ccr2−/− and Ccr2+/+ mice indicated similar tumor growth, suggesting that deficiency of monocyte trafficking has no obvious effect on ID8 tumor growth." (PMID 37932814, 2023). "In accordance, adjuvant epigenetic therapy with low-dose DNMT and HDAC inhibitors disrupts the premetastatic niche by blocking the trafficking of MDSCs through the downregulation of CCR2 and CXCR2 and also favouring MDSC differentiation into anti-tumour macrophage-like cells." (PMID 36161514, 2023). "Although Carlumab was well tolerated by patients, it only resulted in transient suppression of chemokine effects, did not block the CCL2/CCR2 pathway, and exhibit no anti-tumor effect." (PMID 37143666, 2023). "MDSCs are generated in the bone marrow and their recruitment to the tumor site is dependent on diverse set of chemokines, such as CCL2, CCL3 and CCL4, for the recruitment of M-MDSCs via the C-C chemokine receptor 2 (CCR2) and the ligands of the CXC-chemokine receptor 2 (CXCR2) for PMN-MDSC." (PMID 37370739, 2023). "However, once a tumor succeeds in growing and establishes an inflammatory TME, monocyte-derived macrophages recruited via the CCL2/CCR2 axis are rapidly reprogrammed and protect the growing tumor by NK cell inactivation." (PMID 36845555, 2023). "Moreover, it has been reported that several chemokine receptors, such as CCR2 and CXCR4, are expressed on the surface of MSCs, and they are critically involved in the homing potential of MSCs toward tumor tissues." (PMID 36831094, 2023).
tumor (continued). "Losartan has been shown to reduce monocyte recruitment to the TME and suppress tumor growth via inhibition of C-C chemokine receptor type 2 (CCR2) signaling in non-CNS tumors." (PMID 36724255, 2023). "In addition, the tumor tissue of the DEN/CCl4-treated WT mice shows a reduction of chemokine receptors levels compared to the surrounding tissue of the same mouse (Ccr5, Ccr2, Ccr7, Ccr1 and Cxcr4)." (PMID 35897689, 2022). "We divided the 443 TCGA LUAD samples with complete clinical data into high and low groups according to tumor purity, and obtained CSGTPP (0.21*CCR2+ 0.06*GIMAP6+0.64*CD80+ 0.21*IL16) with LASSO regression analysis, and then divided the samples into high and low two groups." (PMID 35280857, 2022). "Next, to determine whether CCR2 was expressed in MDSCs, we performed multicolor immunofluorescence staining for CCR2, Arg1, GR1, and CD11b in the tumor/stromal coxenografts." (PMID 34874922, 2022). "However, combined CCR2 and CXCR2 blockade led to a sustained inhibition of systemic mobilization of both CCR2+ TAMs and CXCR2+ neutrophils, which enabled anti-tumor immune response and potentiated FOLFIRINOX chemotherapy." (PMID 35740692, 2022). "The low intracellular content of ROS is related to the enhanced expression of the homing receptors CCR2, CXCR3 and CCR7, which promote both entry and accumulation of CLL cells in the pro-survival tumor microenvironment of lymphoid organs, eventually enhancing leukemic cell survival." (PMID 35847884, 2022). "Although blocking CCR2 alone was not sufficient to inhibit tumor growth, resistance to BRAFi was abolished when CCR2 antagonists were used in combination with other drugs (anti-CTLA-4 and anti-PD-1 drugs)." (PMID 36077785, 2022). "In vivo studies showed that knockdown of GOT1 expression inhibited tumor formation compared with tumor tissues formed upon exosome induction, which was mediated by promoting ferroptosis via suppressing the protein expression of GOT1, CCR2, Nrf2 and HO-1 in tumor tissues." (PMID 36497150, 2022). "When we evaluated the tumor-infiltrating cell populations, double-K/O tumors presented fewer Iba1+-activated F4/80+ macrophages/microglia, lower secretion of MCP-1 in GFAP-activated astrocytes, and poor expression of CCR2/CCR4 receptors." (PMID 35980743, 2022). "We also investigated the specific association between FAM46C expression and chemokines and their receptors in pan-cancer and found that FAM46C expression was positively correlated with immune chemokines (CXCL9 and CXCL13) and immune chemokine receptors (CCR2 and CCR4) in most tumours (all p < 0.01)." (PMID 35222533, 2022). "Previously, in grafted tumor models, targeting CCR2 resulted in a compensatory influx of neutrophils, something we did not observe here using a different CCR2 inhibitor against autochthonous disease." (PMID 36256464, 2022). "Therefore, targeting CCL2/CCR2 and CXCLs/CXCR2 can potentially regulate immune cell infiltration in the tumor microenvironment and improve the therapeutic effect of HCC." (PMID 36403057, 2022). "Although CCR1, CCR2, CCR3, and CCR5 are widely recognized as the main functional receptors of CCL7, PCa is mainly dependent on the CCR3/CCL7 signaling axis, which contributes to the tumor microenvironment." (PMID 35406450, 2022). "We did observe a 75% reduction in UPS TAMs in the CCR2 KO line but did not observe any change in long-term survival and instead observed earlier onset of tumor volume and BLI reductions following treatment." (PMID 36700206, 2022). "Furthermore, radiotherapy induces a significant increase in the recruitment of CCL2 and Ly6C+CCR2+ monocytes in pancreatic ductal adenocarcinoma (PDAC), thereby accelerating tumor proliferation and angiogenesis." (PMID 35702353, 2022). "While the tumor reduction observed in mice implanted with KPC tumors that had been admixed with CCR2+ trained cells was significant, it was not as striking as mice given IP WGP." (PMID 35140221, 2022).
tumor (continued). "SBRT followed by αPD-1 alone, CCR2/5i alone, or αPD-1 + CCR2/5i suppressed tumor growth in only some of the mice, and SBRT followed by αPD-1 + CCR2/5i + GVAX suppressed tumor growth in all the mice initially up to approximately day 33 (i.e., 33 d from orthotopic tumor implantation)." (PMID 35404390, 2022). "New therapeutic inhibitors of CCR2, such as carlumab and PF-04136309, have been used in clinical trials to block CCL2/CCR2 signaling, leading to inhibition of TAM infiltration, and consequently, reduction of tumor progression." (PMID 35526184, 2022). "In addition, neutrophils can be recruited at the tumor site by CC chemokines acting on CCR1, CCR2, and CCR5, but their targeting must be carefully considered because these chemokines can promote neutrophil antitumor activity." (PMID 35158948, 2022). "Therefore, elevated CCR2 and CCR5 led to the infiltration of mast cells and production of leukotriene B4 (LTB4), which consequently recruited CD8+ T cells into the tumor microenvironment." (PMID 35677043, 2022). "CCR1, CCR2 and CCR3 were reported to be potential receptors of CCL7 in tumor microenvironment." (PMID 35715847, 2022). "Furthermore, several chemokine signaling axes also contribute to tumor vasculature generation such as CXCLs/CXCR2, SDF1/CXCR4, and CCL2/CCR2 axis directly or indirectly." (PMID 36324128, 2022). "Since the CCL2/CCR2 axis is pivotal in inflammatory processes, it is worth evaluating how intervention by modulating the inflammatory properties of the TME can augment anti-tumor immunity." (PMID 36568151, 2022). "Based on the existing evidence, we hypothesized that blocking the CCL2/CCR2 and CXCLs/CXCR2 axes would enhance the TACE-induced inhibition of tumor growth." (PMID 36403057, 2022). "In other studies such CCR2 antagonists showed favourable activities beyond the repression of splenic HSPC recruitment and myelopoiesis, but also impaired myeloid cell survival, Treg homing, and tumor cell growth." (PMID 36561751, 2022). "For instance, one chemokine, i.e., CCL2, might be the prominent driver of CCR2+/CX3CR1+ cell recruitment to the tumor, while the second, i.e., CCL7, is more important for homing to specific niches within tumor." (PMID 36685592, 2022). "Furthermore, through whole-mount imaging of tumor-immune cell-vascular crosstalk in intact lobes based on liver-CUBIC, we characterized an accumulation of CX3CR1+CCR2+F4/80+ macrophages at metastatic foci in early colorectal liver metastases." (PMID 35910800, 2022). "Therefore, CCL2 expression in the tumor microenvironment attracts CCR2-expressing KLRG+ NK cells, leading to enhanced tumor-homing efficiency of NK cells." (PMID 35677043, 2022). "Myeloid-cells tumor homing is largely regulated by multiple ligand-receptor interactions, mainly the colony-stimulating factor-1 (CSF1R), the C-X-C Motif Chemokine Receptor 2 (CXCR2), the C-C chemokine receptor type 2 (CCR2) and type 5 (CCR5)." (PMID 36077813, 2022). "Furthermore, depleting or downregulating M2-TAMs suppressed tumor growth by inactivating CCL2 and/or CCR2 signaling." (PMID 36303162, 2022). "Based on the significant association between the two chemokine axes and HCC, we hypothesized that targeted therapies against CCL2/CCR2 and CXCLs/CXCR2 can improve the anti-tumor effect of TACE." (PMID 36403057, 2022). "In contrast, the tumor take rate in Ccr2–/– mice was not significantly changed, compared to wild-type mice." (PMID 33976133, 2021). "This review will separately discuss the chemotactic and non-chemotactic effects of the CCL2/CCR2 axis on monocytes/macrophages, T cells and tumor cells." (PMID 34804061, 2021). "Indeed, inhibition of CCR2 signaling blocks TAM recruitment and thus reduces TAM frequency, improving the survival of tumor-burdened mice in certain murine tumor models." (PMID 34638388, 2021). "Adoptive transfer of Ly6ChiCD11b+ cells from wt but not CCR2-/- mice resulted in preferential recruitment of monocytes to a tumor cell challenged lung." (PMID 34804061, 2021).